PARP1 (poly(ADP-ribose) polymerase 1)
Diseases named in the same sentence as PARP1 in open-access papers (continued):
Sharing a sentence is not in itself a finding about the gene and the disease.
cancer (continued). "PARP1/2 are post-translational modification enzymes that are pivotal in the repair of single-strand DNA breaks (SSBs) by the base-excision repair (BER) pathway in normal and cancer cells." (PMID 35270034, 2022). "All these mechanisms can be targeted simultaneously with synergistic effects, thus explaining why lower doses of PARP-1 inhibitors are needed to confer efficacy in non-oncological conditions, compared to cancer." (PMID 35158955, 2022). "The previous studies demonstrated that autophagy was initiated in a series of cancer cell lines after the treatment of PARP-1 inhibitors, but no report for HCT-116 cell lines." (PMID 36353483, 2022). "Therefore, inhibition of PARP-1 has been shown to conserve NAD+ levels in the cell but severely hinders DNA damage detection and repair, an effect beneficial for cancer chemotherapeutic procedures and for some muscle disorders." (PMID 35203360, 2022). "We also found that the expression of cleaved PARP1 and cleaved caspase-3 increased in the RO + CQ group, indicating that the combination of the NGF inhibitor RO and the autophagy blocker chloroquine can induce the apoptosis of cancer cells." (PMID 35109895, 2022). "Furthermore, recent literature has demonstrated that PARP1 inhibition and PARP1-DNA trapping are key for antitumor activity in HRD cancer models." (PMID 36756144, 2022). "This can be explained by a possible lack of the enzymatically active PARP1 in MCF10A in contrast to the cancer cell-lines." (PMID 35008392, 2022). "Besides the role of PARP1, TNKS1–2poly-ARTs are currentlybeing investigated as potential therapeutic targets in cancer mainlydue to their role in controlling the Wnt/β-catenin signalingpathway." (PMID 35608571, 2022). "SNORA74A activates PARP1-directed DExD-box helicase 21 (DDX21) ADP-ribosylation and increases the nuclear localization of DDX21 protein, thereby promoting ribosomal biogenesis and cancer cell growth." (PMID 36566215, 2022). "PARP1 maintains cellular functions, including DNA repair/maintenance of genomic integrity, DNA methylation, chromatin regulation, and histone modification and helps in the recruitment of HDAC1 and HDAC2 as chromatin modifications in cancer." (PMID 35059624, 2022). "In cells lacking HR, such as BRCA1/2 deficient cancer cells, TMEJ serves as an essential backup mechanism that still allows resected DSBs to be repaired through the activity of PARP1, DNA ligase III and Polθ (encoded by POLQ)." (PMID 35567571, 2022). "Dual-inhibitors of PARP1 and PARP2 are promising anti-cancer drugs." (PMID 35349716, 2022). "Similar to other carcinoma, in EC various tumor suppressor gene promotors (MLH1, PTEN, p16, APC, MGMT, RASSF1, PR and CDH1) are hypermethylated, whereas oncogene promotors (BMP, CTCFL, PARP1, CASP8) are hypo- or demethylated." (PMID 35284957, 2022). "Given the variability of cellular levels of NAD+ across different organs and the numerous mechanisms of NAD+ biosynthetic pathways that are altered in cancer, clarifying the essential role of NAD+ in PARP1 activation and the cellular response to DNA damage is essential." (PMID 34806016, 2021). "In addition, NAMPT regulation of cancer stem cell pathways correlated with SIRT1 and PARP1, as these proteins seem to play important roles in the CSC phenotype acquisition promoted by NAMPT." (PMID 33384409, 2021). "Over the past decade, many PARP-1 inhibitors have been reported, and the FDA has approved olaparib, rucaparib, niraparib, and talazoparib for the intervention of a variety of cancers." (PMID 34069967, 2021).
cancer (continued). "The overexpression of the tumor suppressor PARP1 implies non-oncogene addiction of many cancer cells, relying on DDR and repair pathways for survival." (PMID 33498235, 2021). "Cancer cells appear to have taken advantage of the NNMT/NAMPT pathway to promote the neoplastic phenotype by increasing the activity of NAD+-dependent processes such as sirtuins and PARP-1." (PMID 34680055, 2021). "Iniparib was the first potent PARP1 inhibitor, effective against cancer cell lines with 40–128 μM IC50 values, and is not toxic at 200 mg/kg in Syrian hamsters." (PMID 34829741, 2021). "The three clusters generated contained genes or proteins involved in apoptosis (BIRC3, BIRC5, PARP1, CASP8, and CASP9), transcriptional dysregulation in cancer (CDKN1B, RELA, CDKN1A, MYC, JUN, and MMP9), and cancer progression (CCND1, CASP3, CTNNB1, WNT1, and VEGFA) pathways." (PMID 34836311, 2021). "Olaparib is a clinically used PARP1-i chemotherapeutic agent that is especially effective for treatments of BRCA1 or BRCA2 negative cancers, such as ovarian and breast cancer types." (PMID 33926008, 2021). "Moreover, CSNK2A1 renders cancer cells resistant to apoptotic stresses by activating BCL2 and suppressing PML, FOXO3, and PARP1." (PMID 34359939, 2021). "PARP-1 are involved in DNA repair damage and so PARP-1 inhibitors have been used as potentiators in combination with DNA damaging cytotoxic agents to compromise the cancer cell DNA repair mechanism, resulting in genomic dysfunction and cell death." (PMID 35424391, 2021). "The possible roles of NAD+ synthesis and PAR-degrading enzymes have not yet been investigated as possible targets in cancer even though the effects of PARP1 and PARG inhibition often result in similar rather than opposite outcomes in DNA damage scenarios." (PMID 33922595, 2021). "In contrast, there are currently four approved small molecule inhibitors of PARP-1, namely, Olaparib, rucaparib, talazoparib, and niraparib, which target PARP-1′s function and activity at the protein level and are used for several forms of cancer." (PMID 34698261, 2021). "In our hands, the glycolytic capacity of irradiated cancer cells was higher when cells were treated with the PARP inhibitor PJ34 compared with cells receiving irradiation only, corroborating a role of PARP1 activity in the rapid decline of glycolytic activity in irradiated cancer cell line panel." (PMID 34825138, 2021). "Thus, given the key roles of PARPs, especially PARP1 and PARP2, in repairing cytotoxic chemotherapy-induced DNA damage, they have attracted attention as a new therapeutic strategy for cancer." (PMID 34356835, 2021). "PARP1 is aberrantly expressed in different cancers, where its overexpression rather than underexpression is associated with genomic instability, likely due to accumulation of errors through increased MMEJ." (PMID 33541355, 2021). "First, we selected the down-regulated genes at PNX0010 under PARG overexpression that are related to cancer development: ID1, ID2, ID3, and SERPINE1 and performed qPCR analysis for 786-O, 769-P, SK-RC-45, and SK-RC-26b cell lines treated with the 10 uM PARP-1 inhibitor rucaparib for 24 h." (PMID 34638458, 2021). "PARP-1 antagonizes the activity of the PI3K/Akt pathway; the PI3K/Akt pathway enhances glycolytic flux through glucose transposters (GLUTs), HK, and PFK2, and promotes nucleotide, protein, and lipid biosynthesis and autophagy in cancer." (PMID 33922595, 2021). "Normal cells do not divide as frequently as cancer cells, which allows them to survive PARP1 inhibition." (PMID 34461785, 2021).
cancer (continued). "4T1 cancer cells showed no PARP-1 cleavage upon treatment with either Nav or HNav, further demonstrating no activity of the compound in these cells." (PMID 33562504, 2021). "PARP1 and PARP2 are two key enzymes that are critical for repairing single-strand breaks (“nicks”) in the DNA – a mechanism which is critical for the survival of both normal and cancer cells." (PMID 34461785, 2021). "To evaluate whether FOXM1 is a valuable target, we analyzed the differential expression of FOXM1, PARP1, and PARP2 between cancer tissues and adjacent normal tissues in 31 cancers from the TCGA projects." (PMID 34880209, 2021). "The treatment of the tested cancer cell lines with the 3-AB agent alone generated non-significant alterations in the PARP1/ACTB mRNA cellular content (data not shown)." (PMID 34440232, 2021). "Cytotoxic activity against cancer cells was enhanced in probiotic-fed compared to control mice, as evidenced by the elevation of apoptotic markers, such as cleaved caspase 3 and poly (ADP-ribose) polymerase 1 (PARP1), in tumor tissue." (PMID 32033490, 2020). "It is now emerging that PARP-1 and PARP-2 may not only impact cancer cell biology, but also modulate the anti-tumor immune response." (PMID 32046278, 2020). "The nicks accumulated due to the lack of PARP1/2 enzymatic activity can then be converted to DNA double-strand breaks (DSBs) in replicating cancer cells to activate DNA damage checkpoints and eventually lead to cell death." (PMID 32890402, 2020). "To delineate which cell type in the myeloid lineage, other than osteoclasts, confers the differential regulation of bone metastasis by PARP1 and PARP2, we performed flow cytometry analyses (FACS) of bone marrow cells isolated from mice receiving cancer cells via intracardiac injection." (PMID 32221289, 2020). "Across progression trajectories, our results show that expression of genes related to ADP‐ribosylation decreased as tumors progressed (while PARP1 and PARP2 increased or remained stable), suggesting the potential for a differential response to PARP inhibitors based on cancer progression." (PMID 32207233, 2020). "Poly (ADP-ribose) polymerase (PARP)-1 and PARP-2 are key players in cancer." (PMID 33187221, 2020). "PARP1 inhibition in CCL2 expressing cancer cells can alter not only the cancer cells themselves but also the surrounding cells in tumor stroma." (PMID 32455851, 2020). "Understanding the immunomodulatory roles of PARP-1 and PARP-2 may provide invaluable clues to the rational development of more selective PARP-centered therapies which target both the cancer and its microenvironment." (PMID 32046278, 2020). "Despite the growing attention paid to PARP1 in the past two decades, a fully effective treatment for cancer-diagnosed patients has not been discovered yet." (PMID 32900001, 2020). "We first examined the individual roles of PARP1 and PARP2 in cancer cells." (PMID 32221289, 2020). "ChIP assay showed that β-catenin binding at CCL3 promoter was significantly augmented by the KD of PARP2 but not by PARP1 in cancer cells." (PMID 32221289, 2020). "PARP1 inhibitors disturb the single strand repair that causes persistent double strand breaks and lethality in BRCA1-deficient cancers lacking the capacity for HR repair." (PMID 32405340, 2020). "Thus, inhibition of cMET is an attractive strategy to indirectly block PARP1-mediated DNA repair and enhance the therapeutic effects of PARP inhibitors in cancer cells." (PMID 32295316, 2020).
cancer (continued). "Previous study showed that PARP1 hyperactivation leads to therapeutic resistance, and the therapeutic potential of PARP inhibition in combination with cisplatin has shown profound anti-cancer effect in cervical cancer." (PMID 32711558, 2020). "The ATL-induced, cancer-specific ROS increase was followed by NAC-suppressible accumulation of 8-oxoG, DNA strand breaks and PAR, indicating generation of oxidative DNA damage and activation of PARP1/2." (PMID 32029902, 2020). "In addition, we have shown that in the physiological state there is a positive relationship between PARP1, PARP2, and TRPM2, which is disturbed in cancer cells." (PMID 32423430, 2020). "Intriguingly, since HR is often up-regulated in cancerous cells, one would expect that blocking PARP1 with olaparib would sensitize cancer cells rather than normal cells to chemicals inducing DNA DSBs." (PMID 31291457, 2019). "Thus, even with wildtype PARP-1, the mice obtained by crossing 129Sv with TRAMP mice would be expected to be more cancer-prone than TRAMP mice alone." (PMID 30691122, 2019). "Considering the multiple functions of PARP1 including cell proliferation and DNA repair, it was not surprising to find high expression associated with shorter MFS, as already reported in other cancers." (PMID 31131495, 2019). "The PARP1 enzyme assay showed that the efficiency of PARP-1 inhibition by (BZP) was slightly less than that of staurosporine, while BZP-NPs inhibited the enzyme efficiently as staurosporine in MCF-7 or to a greater extent in case of MDA-MB-231 cancer cells." (PMID 31261939, 2019). "Greater understanding of how LMP1 is able to manipulate the host gene regulatory machinery through chromatin-modifying enzymes, such as PARP1, may be exploited by therapeutic intervention to better treat EBV-positive cancers." (PMID 30395643, 2018). "To clarify the relationship among PARP1, arginase II, eNOS, NO and endothelial function in vivo, we used PARP1-/- mice, an animal model for cancer research, with or without a high-cholesterol diet." (PMID 30158868, 2018). "Numerous important signaling molecules are dependent on NAD+ as a co-factor in their mechanisms of action, such as PARP1, which is involved within DNA damage repair and could be an additional linkage between NLRX1 and cancer." (PMID 29535731, 2018). "Similarly, Parp-1 directly interacts with the HIF-1α protein and contributes to its activation in several human cancer cell lines as well as murine embryonic fibroblasts." (PMID 29755367, 2018). "Additionally, it would be interesting to identify which signaling pathways are regulated by methylated PARP1 and to determine how PARP1 methylation affects the response to PAPRP1 inhibitors, which are currently in cancer Phase II clinical trials." (PMID 30013796, 2018). "The main achievement of PARP1 in cancer is stimulation for proliferation of colorectal cancerous cells, whereas there is no research on PARP1 functional mechanism in NSCLC." (PMID 29152079, 2017). "Olaparib-induced mitotic chromatid scattering was observed in various cancer cell lines with increased protein levels of PARP1 and PARP2, but not in non-cancer or cancer cell lines that expressed lower levels of PARP1 or PARP2." (PMID 29262611, 2017). "In cancer cell models, the cellular miRNA “miR-124” has been shown to regulate PARP-1, whereas miR-223 expression was negatively correlated with PARP-1 levels." (PMID 28828398, 2017). "Other drug targets for cancer therapeutics with high CAP scores include MAP4 (60%) and TUBB1 (30%), which are targets of paclitaxel, MAP1A (42%), a target of estramustine, CD3G (39%), a target of muromonab, and PARP1 (37%), a target of olaparib." (PMID 29273096, 2017). "Indeed, the crucial role of PARP1 expression was confirmed in several BSTS histotypes and in other cancer types as well." (PMID 28454547, 2017).
cancer (continued). "At least five of the inhibitors block the function of Tdp1 and PARP1, which have been identified as essential cellular proteins for HPV replication and promising candidates for the development of antivirals against HPV and possibly against HPV-related cancers." (PMID 28182794, 2017). "These include cancer hallmarks of various types: oncogenes (BCL2, BRAF), caspases (CASP6/7), transcription factors (E2F3), cell cycle genes (CDC42, CDK2, CDKN2A), cancer related kinases (JAK2/3, MAPK4/6/14) and DNA repair genes (BRCA1, PARP1 and RAD50)." (PMID 28059167, 2017). "PARP1 inhibitors are widely used as drugs that target these BRCA1 and 2-mutant cancers." (PMID 28756516, 2017). "In response to NQO1 activation-triggered oxidative stress, the adaptively activated salvage NAD+ synthesis is insufficient to compensate for the PARP-1 activation induced rapid depletion of NAD+, rendering the cancer cells more reliant on the de-novo NAD+ synthesis from tryptophan." (PMID 27566573, 2016). "PARP1 overexpression is believed to be due to the increased DNA damage occurring in genetically unstable cancer cells, rather than the activation of specific oncogenic pathways." (PMID 26900125, 2016). "Our results indicated that NTP or NTPO treatment in human cancer cells could induce ATR-mediated cell-cycle checkpoints and PARP1-dependent DNA repair." (PMID 27145275, 2016). "Autoantibodies to proteins involving in the synthetic lethal interaction (PARP1 and BRCA1/2) might act as potential biomarkers for diagnosis of cancer." (PMID 25865228, 2015). "Autoantibody frequency to PARP1, BRCA1, and BRCA2 in cancer varied from 0% to 50%." (PMID 25865228, 2015). "Interestingly, preclinical evidence indicates that both PARP1 and PHB2/PHB are excellent therapeutic targets in cancer." (PMID 25200342, 2014). "Because of the crucial role of PARP1 in response to DNA damage, PARP1 inhibition was identified as a potential therapeutic target to enhance the efficacy of DNA damage agents, or to certain cancer cells lacking homologous recombination repair." (PMID 23762475, 2013). "There is still considerable interest in both competitive and non-competitive PARP1 inhibitors as therapeutic agents in cancer treatments." (PMID 24202319, 2013). "Thus, targeting PARP-1 and PARG are strategies to inhibit their genome-protecting effects in cancer cells and thereby induce cancer cell death." (PMID 23254695, 2013). "PARP-1 has also been shown to bind the inhibitory element of COX-2, which mediates inflammation and promotes VEGF-mediated pro-angiogenesis pathways activated in cancer cells." (PMID 24350055, 2013). "There are four categories of known and potential mechanisms of resistance to PARPi in cancer cells, which are described below: (i) increased HR capacity; (ii) altered NHEJ capacity; (iii) decreased levels or activity of PARP-1, and (iv) decreased intracellular availability of PARPi." (PMID 23450678, 2013). "PARP-1 inhibition may reduce PAR-mediated inactivation of caspase-8, sensitizing cancer cells to tumor necrosis factor-related apoptosis-induced ligand (TRAIL) therapy." (PMID 24350055, 2013). "Given the availability of effective therapies that exploit defects in homologous recombination, such as PARP-1 inhibitors and cisplatin, it is increasingly important to determine whether these therapies are likely to be effective in ER+BRCA1-mutant cancers." (PMID 24137399, 2013). "In conjunction, PARP-1-induced depletion of ATP stimulates AMP-activated protein kinase (AMPK) while inhibiting mTOR to promote autophagy, yet another cell death pathway important in cancer survival and treatment response." (PMID 24350055, 2013). "As such, PARP1 expression is often elevated and its ADP-ribosylation activity increased in cancerous tissues, rendering it a good candidate for sensitizing cancer cells to the cytotoxic effects of DNA damaging agents." (PMID 24970148, 2012).